RAB15 (RAB15, member RAS oncogene family)
Description:
The small GTPases Rab are key regulators of intracellular membrane trafficking, from the formation of transport vesicles to their fusion with membranes (By similarity). Rabs cycle between an inactive GDP-bound form and an active GTP-bound form that is able to recruit to membranes different sets of downstream effectors directly responsible for vesicle formation, movement, tethering and fusion (By similarity). RAB15 may act in concert with RAB3A in regulating aspects of synaptic vesicle membrane flow within the nerve terminal (By similarity).
Tractability: Antibody: UniProt places it where antibodies can reach, with high confidence; its Gene Ontology location is reachable by antibodies, with medium confidence. PROTAC: ubiquitination databases record sites on it; its protein half-life has been measured.
Gene: Protein-coding gene on chromosome 14 (64,945,814 to 64,973,226, reverse strand). Ensembl gene ENSG00000139998.
Subcellular location: Cell membrane
Subcellular location (Human Protein Atlas): Centriolar satellite; Vesicles
Pathways (Reactome):
Metabolism of proteins: RAB geranylgeranylation
Gene Ontology:
Molecular function: G protein activity; protein binding; GTPase activity; GTP binding
Biological process: positive regulation of regulated secretory pathway; receptor-mediated endocytosis; exocytosis; Rab protein signal transduction
Cellular component: cilium; cytoplasm; endosome membrane; extracellular exosome; perinuclear region of cytoplasm; plasma membrane
Genetic constraint (gnomAD): Loss-of-function variants: 12 observed, 28.34 expected, observed/expected ratio (o/e) 0.42, 90% interval 0.27 to 0.69. The upper end of that interval is the gene's LOEUF score, 0.69, which puts it in group 2 of 6, group 1 being the genes least tolerant of losing a copy. Missense variants: 203 observed, 246.74 expected, observed/expected ratio (o/e) 0.82, 90% interval 0.73 to 0.92. Synonymous variants: 95 observed, 96.46 expected, observed/expected ratio (o/e) 0.98, 90% interval 0.83 to 1.17.
Homologues: Orthologues: macaque RAB15 (99% identical), dog RAB15 (99% identical), mouse Rab15 (99% identical), pig RAB15 (98% identical), rat Rab15 (98% identical), tropical clawed frog rab15 (87% identical), guinea pig RAB15 (79% identical), zebrafish rab15 (78% identical), rabbit RAB15 (75% identical), chimpanzee RAB15 (58% identical). Paralogues in human: RAB8A (44% identical), RAB8B (44% identical), RAB10 (43% identical), RAB13 (43% identical), RAB1B (42% identical), RAB1A (41% identical), RAB11A (40% identical), RAB26 (40% identical), RAB3D (40% identical), RAB11B (40% identical), RAB35 (40% identical), RAB12 (39% identical), and 56 more.
Diseases named in the same sentence as RAB15 in open-access papers:
RAB15 is named in the same sentence as 13 diseases in open-access papers, as found by Europe PMC text mining. Sharing a sentence is not in itself a finding about the gene and the disease. The quoted sentences say what the papers report.
lung carcinoma (4 papers, 2014 to 2025). "Zhang’s group selected a panel of five urinary molecules (ferritin light chain, mitogen-Activated Protein Kinase 1 Interacting Protein 1-Like, fibrinogen Beta Chain, two Member RAS Oncogene Family, RAB33B and RAB15) as a predictive model to differentiate lung cancer from healthy lung tissue." (PMID 33923502, 2021).
glioma (1 paper, 2020). A benign or malignant brain and spinal cord tumor that arises from glial cells (astrocytes, oligodendrocytes, ependymal cells). "RAB15 interacts with FGFR1 involved in the recycling of glioma cell receptors and can be used as a pharmacological target to inhibit or down-regulate the proliferation of tumors by stimulating degradation." (PMID 33193654, 2020).
hypopharyngeal cancers (1 paper, 2022). Carcinoma, predominantly squamous cell, arising from the epithelial cells of the hypopharynx. "Herein, we newly demonstrated that 4 genes (and the proteins) as the most powerful exploratory markers for response prediction to TXT, CDDP, and 5-FU- namely, AGR2, and PDE4D for TXT; NINJ2 and possibly RAB15 for CDDP, and CDC25B for 5-FU- in hypopharyngeal cancers." (PMID 35841085, 2022).
Immunodeficiency (1 paper, 2024). Failure of the immune system to protect the body adequately from infection, due to the absence or insufficiency of some component process or substance. "Rab15 is involved in positive regulation of regulated secretory pathway-associated immunodeficiency." (PMID 38474724, 2024).
neuroblastoma (1 paper, 2014). Neuroblastoma (NB) is the most common solid, extracranial childhood tumor. "RAB15 was originally identified as a brain-tissue specific RAB protein within the RAB family of small G proteins that regulates the endocytic recycling pathway and is associated with the retinoic acid-induced differentiation of neuroblastoma cells." (PMID 25411851, 2014).
cancer (5 papers, 2018 to 2022). A tumor composed of atypical neoplastic, often pleomorphic cells that invade other tissues. "Among potential GSDMB interacting cancer and autophagy proteins, some Rab GTPases were found (Rab5C, Rab7A, Rab9A and Rab15)." (PMID 36163066, 2022). "However, with GCH = 26.14 in the malign part and 1.41 (18.5x smaller) in the normal tissue, the 2.71x significantly up-regulated member of the RAS oncogene family RAB15 may be therapeutically actionable for this person as reported for other cancer cases." (PMID 29416781, 2018). "The 2-fold upregulated gene RAB15 is known as a member of RAS oncogene family, but to judge, to what extent it acts as an oncogene itself or might be able to affect proliferation of cancer cells, more research on its specific functions is necessary." (PMID 31357971, 2019).
tumor (3 papers, 2022 to 2025). "Analysis of the GSE39582 dataset revealed notably elevated expression of CCDC34, FBL, and RAB15 in tumor tissues, whereas AQP11 and HADH were notably downregulated." (PMID 41583431, 2025).
infection (2 papers, 2013 to 2024). The state of being infected such as from the introduction of a foreign agent such as serum, vaccine, antigenic substance or organism. "To test this, we overexpressed miR-214 in Huh-7 cells by infection with lenti-pri-miR-214 lentiviruses, which resulted in a decrease of the level of Rab15 protein." (PMID 24386085, 2013). "Infection of lenti-pri-miR-214 could also repress the pGL3-Rab15-3′UTR luciferase reporter activity, supporting that miR-214 could repress the expression of Rab15 through targeting its 3′UTR." (PMID 24386085, 2013).
RAB15 also shares sentences with these, for which no sentence is quoted: bladder cancer (1 paper); cervical cancer (1); colorectal cancer (1); small cell lung carcinoma (1); virus infection (1).